PAX3 (paired box 3)
Diseases named in the same sentence as PAX3 in open-access papers (continued):
Sharing a sentence is not in itself a finding about the gene and the disease.
melanoma (continued). "Among these genes MITF, WNT/beta Catenin, SOX9, SOX2, PAX3, RANK/RANKL are important in melanocyte differentiation and melanoma." (PMID 25612317, 2015). "Genes upregulated in this cluster include known markers of the melanocyte lineage and melanoma such as SOX10, MITF and PAX3." (PMID 25865119, 2015). "Although positive regulation of MITF by PAX3 in melanocytes is well described, PAX3 is thought to function independently of MITF or even play a repressive role on MITF expression in melanoma." (PMID 25433395, 2015). "The precise relationship and the interplay between PAX3, MITF and BRN2 in melanocytes and melanoma cells needs to be further investigated." (PMID 25880082, 2015). "SOX10, PAX3, and MITF participate in regulation of MET (HGF receptor), which is expressed at high levels in human melanoma." (PMID 24743024, 2014). "MITF and PAX3 bind directly to the MET promoter; coexpression of these three proteins is found in melanoma biopsies." (PMID 24743024, 2014). "We previously characterized a panel of melanoma cell lines for expression levels of MITF and PAX3, and cell migratory behaviors." (PMID 24062982, 2013). "We present here several lines of experimental evidence supporting the notion that PAX3 and MITF expression indeed play independent roles in melanoma progression and cell migration." (PMID 24062982, 2013). "They showed that PAX3 promoted a less differentiated, stem-like (via HES1, SOX9, NES, DCT), motile (via MCAM, CSPG4, and CXCR4) phenotype, characteristic of melanomas with high metastatic potential." (PMID 24069584, 2013). "This predicts that PAX3 and MITF play distinct roles in signaling pathways that promote melanoma progression, and also predicts additional features expected in melanoma cells undergoing phenotype switching." (PMID 24062982, 2013). "In the first approach we used dual label immunofluorescence to compare the relative expression of PAX3 and MITF in adjacent regions within the same melanoma tissue section." (PMID 24062982, 2013). "This review has focused on five molecules involved in melanoma metastasis – MCAM, Gal-3, CSPG4, MMP-2, and PAX-3." (PMID 24069584, 2013). "In conclusion, here we have presented new evidence that PAX3 and MITF expression have independent and opposing effects in melanoma." (PMID 24062982, 2013). "The exception is melanoma metastases, in which BCL2L1 was detected in only one sample (out of four) and both PAX3 and BCL2L1 were weakly stained and very rarely co-stain." (PMID 20421967, 2010). "In addition, our findings that PAX3 expression is specific for both the melanocytic lineage and melanocytic lesions, could have potential applications in the clinical setting, as an immunohistochemical assay for the differential diagnosis of melanoma." (PMID 20421967, 2010). "We have observed that a similar proportion of PAX3-positive cells were also BCL2L1-positive in melanocytes of normal skin, in naevi and in melanoma cells in all of the samples analysed." (PMID 20421967, 2010). "This is the first study to perform a non-biased genomic screen to reveal a PAX3 cistromic signature in melanoma cells." (PMID 40428399, 2025). "While PAX3 is important in both melanocytes and melanoma, gene signature studies have not been performed on a whole genome scale." (PMID 40428399, 2025). "Additionally, NOTCH, WNT, and SOX family members, as well as MITF, Paired Box 3 (PAX3), and Forkhead Box D3 (FOXD3) are essential for early neural crest development and have been reviewed in the context of initiating EMT in melanoma." (PMID 38426087, 2024). "Finally, PAX3 (paired box gene 3 transcription factor) was shown, in conjunction with the transcription factor ETS1, to promote melanoma cells proliferation and metastasis by increasing the expression of MET, the HGF receptor." (PMID 35052351, 2021). "Overexpression of c-Met may be accomplished through the action of transcription factors PAX3 and ETS1, and these factors can be targets to repress melanoma tumor growth." (PMID 33807778, 2021).
melanoma (continued). "In the absence of fibroblasts, melanoma differentiation is driven by collagen stiffness via the YAP/PAX3/MITF axis." (PMID 33922284, 2021). "To further elucidate the inhibitory mechanism, we investigated the effect of VP on the SRY (sex determining region Y)-box 10 (SOX10) and paired box gene 3 (PAX3) transcription factors that regulate melanoma markers such as protein melan-A (MART-1) and MITF expressed in melanoma cells." (PMID 33672928, 2021). "Clinical trials: In melanoma, MITF and its upstream activator, PAX3, are drivers of an early non-mutational and reversible drug-tolerant state." (PMID 33322354, 2020). "Furthermore, IPA protein-protein interaction (PPI) analysis for co-module #12 showed that melanoma-related transcription factors, such as MITF, PAX3, SOX8, and SOX10, formed a sub-network." (PMID 29950679, 2018). "The model provides that, although melanoma cells switch back to their embryogenetic program, PAX3 in CMM does not modulate MITF expression as it accounts for neural crest formation." (PMID 29156734, 2017). "Pax3 also facilitates the malignant progression of RMS and melanomas." (PMID 28638414, 2017). "Moreover, MYSM1 was highly expressed and co-localized with PAX3 and c-MET in melanoma cells in culture and in SSM samples in situ." (PMID 28978033, 2017). "The absence of differential expression of PAX3 in melanocytes of normal human skin, nevi, and melanomas has been also reported." (PMID 27428965, 2016). "To confirm these findings, we investigated these downstream target gene expression profiles in the metastatic melanoma cell line, A2058, following PAX3 silencing (data not shown) and found similar results to those observed in M14 melanoma cells." (PMID 25880082, 2015). "To address whether changes in PAX3 or SOX10 levels might be responsible for the effect of IL-1ß, we performed quantitative RT-PCR and Western Blot analyzes in several melanoma cell lines." (PMID 25853464, 2015). "Importantly, TGFβ treatment leads also to a significant reduction in PAX3 and MITF expression in melanoma cells and this correlates with the growth suppressor activity of this cytokine." (PMID 25818589, 2015). "PAX3 mRNA also contains a single miR-211 binding site, and the over-expression of miR-211 reduces PAX3 expression in melanoma cells (data not shown)." (PMID 25880082, 2015). "Melanoma cells resistant to the cytotoxic effects of MEK inhibitors counteracted TGF-β signaling through overexpression of the E3 ubiquitin ligase SMURF2, which resulted in increased expression of the transcription factors PAX3 and MITF." (PMID 24743024, 2014). "It is interesting to note that even though activation of Mitf by Pax3 during embryogenesis is well described, this regulatory axis does not seem to be operational in melanoma cells, where MITF and PAX3 regulate diverging pathways." (PMID 24069584, 2013). "Our earlier investigations are, to our knowledge, the only comprehensive investigations systematically addressing this notion, demonstrating that PAX3 does not transcriptionally activate MITF in melanoma cells." (PMID 24062982, 2013). "Taken together with earlier published data, the evidence suggests that there are distinct roles for PAX3 and MITF in melanoma progression and melanoma cell migration, thus providing supporting evidence for one of the key predictions of the genetic switch theory." (PMID 24062982, 2013). "We reported previously that PAX3 is extensively expressed in melanocytes, nevi and melanoma tissues, and that expression levels of PAX3 and MITF are highly variable in melanoma cell lines, and are not concordant with each other, especially comparing individual melanoma cells in culture." (PMID 24062982, 2013). "Several experimental approaches were used to investigate whether PAX3 and MITF expression and function were independent in melanoma cells and tissues." (PMID 24062982, 2013).
melanoma (continued). "Here we extend a hypothesis that we previously suggested; that PAX3 and MITF play independent roles in melanoma progression." (PMID 24062982, 2013). "Neither BRN2 nor PAX3 transcription was elevated in melanoma cells in which ATF2 expression was inhibited." (PMID 21203491, 2010). "This belief has been supported by reports detailing the absence of PAX3 expression in melanocytes of normal human skin in contrast to naevi and melanomas." (PMID 20421967, 2010). "Since the precise role played by PAX3 in melanomas is not clear, we have looked into potential PAX3 regulated pathways within normal melanocytes." (PMID 20421967, 2010). "An example of this is MITF, which is not always regulated by PAX3 in melanoma." (PMID 40428399, 2025). "Also, the reduction was closely related to the suppression of PAX3 (paired box gene 3) expression, as compared to the control group (mice with melanoma but not treated with the extract) and, thus, the regulation of PTEN/PI3K/Akt signaling." (PMID 40699824, 2025). "The co-localization of PAX3 and the proliferation marker Ki-67 in melanoma cells, but not in healthy melanocytes, suggests that PAX3 may be associated with increased proliferative capacity and tumor growth." (PMID 40216818, 2025). "While PAX3 target genes have been identified using a candidate approach, non-biased cistromic screens have been limited overall and are nonexistent for melanocyte or melanoma cells." (PMID 40428399, 2025). "Moreover, overexpression of PAX3 (paired box homeotic gene 3) or activation of STAT3 led to vemurafenib, a selective inhibitor of Braf, resistance in melanoma cells, and silencing of PAX3 and STAT3 reduced growth of vemurafenib resistance melanoma cells." (PMID 34577615, 2021). "This suggests that in melanoma cells TGFβ can trigger a switch from YAP/PAX3-driven transcription to SMAD/YAP/TEAD-driven transcription, an idea that is further supported by the fact that TGFβ suppresses PAX3 expression, thus reducing the amount of PAX3 available for YAP binding." (PMID 29545604, 2018). "Thus, PAX3, a well-known transcriptional regulator of MITF, is upregulated during MAPKi treatment, which is also seen within 48 hr in a panel of BRAF mutant melanoma cell lines." (PMID 26977879, 2016). "We therefore examined the therapy phase before acquired resistance had developed and discovered the melanoma survival oncogene MITF as a driver of an early non-mutational and reversible drug-tolerance state, which is induced by PAX3-mediated upregulation of MITF." (PMID 26977879, 2016). "discover PAX3-mediated overexpression of MITF as a reversible resistance mechanism to MAPK-pathway inhibition in BRAF mutant melanomas and identify nelfinavir, which inhibits this mechanism and sensitizes not only BRAF mutant but also BRAF and NRAS mutant melanoma cells to MAPK-pathway inhibitors." (PMID 26977879, 2016). "It is possible then, that its removal allows other PAX3 isoforms to bind to their specific target genes and activate their transcription, i.e. the down-regulation of PAX3E in melanoma cells may facilitate expression of genes responsible for proliferation and survival of melanoma cells." (PMID 25880082, 2015). "While the results presented in this paper provide further insight into the roles of PAX3 in melanocytes and melanoma cells, they may not fully explain the differential functions of PAX3." (PMID 25880082, 2015). "One prediction is that independent and opposing roles for MITF and PAX3 in melanoma would be expected, and we present empirical evidence supporting this: in melanoma tissues PAX3 expression occurs independently of MITF, and PAX3 does not play a key role in melanoma cell proliferation." (PMID 24062982, 2013). "Whether or not a combination of MCAM, MMP-2, CCPG4, PAX-3, and Gal-3 can identify those thin melanomas that comprise the 5% that will develop metastases at a later stage will require further studies of clinical material." (PMID 24069584, 2013).
melanoma (continued). "Furthermore, we show that knockdown of PAX3 inhibits cell migration in a group of “lower MITF” melanoma cell lines, while knockdown of MITF promotes cell migration in a complementary “higher MITF” group of melanoma cell lines." (PMID 24062982, 2013). "Indeed, amongst several melanoma cell lines that we have examined previously, we observed relatively large fluctuations in MITFm expression, and the variations in PAX3 expression level were not as great as MITFm." (PMID 24062982, 2013). "Several studies report PAX3 expression in naevi and melanomas, and show no expression in melanocytes of normal skin, thus concluding that PAX3 re-expression might be involved in melanocyte transformation." (PMID 20421967, 2010). "PAX3 was also co-expressed with melanoma cell migration marker MCAM in dermal naevi and melanoma cell nests, but this downstream target of PAX3 was not present in normal epidermal melanocytes, suggesting differential roles for PAX3 in normal epidermal melanocytes and melanoma cells." (PMID 20421967, 2010). "These heterogenous melanoma subpopulations are characterized by the expression of MITFhigh and MITFlow proteins, MITF and BRN2 (non-canonical melanoma tumor-suppressor) proteins, and MITF and PAX3 proteins." (PMID 38275910, 2024). "Nelfinavir increased the amount of SMAD2 and consequently nuclear phospho-SMAD2 in melanoma cell lines in the absence of exogenous TGF-β, and, importantly, this correlated with the reduction in PAX3 and MITF expression." (PMID 26977879, 2016). "Nelfinavir also sensitized NRAS mutant melanoma cells to MEK inhibition and reduced PAX3 and MITF expression, whereas no sensitization was seen in the KRAS mutant colon cancer cell line HCT116." (PMID 26977879, 2016). "PAX3 is activated by PI3 K (phosphatidylinositol 3-kinase) and STAT3 (signal transducer and activator of transcription 3) in melanoma cells, and a negative PAX3-dependent regulation of MITF expression is mediated by BRN2 encoded by POU3F2." (PMID 25433395, 2015). "We have also previously reported that PAX3 does not transcriptionally activate MITF in melanoma cells, an observation contrary to that outlined in a number of contemporary melanoma research papers." (PMID 24062982, 2013). "Firstly, we show that in melanoma tissues expression of MITF and PAX3 occur independently, and are variable from region to region, and furthermore that the expression of PAX3 is not correlated with Ki67 expression, a marker of cell proliferation." (PMID 24062982, 2013). "In contrast to PAX3, no data exist about the expression and function of PAX2 in melanoma development and progression." (PMID 21876729, 2011). "On a stiff matrix when YAP is nuclear and co-localizes with PAX3, YAP depletion resulted in a significant decrease in MITF expression, but there was no contribution of YAP to MITF expression in melanoma cells grown on a 0.2 kPa soft matrix when the majority of YAP is cytoplasmic." (PMID 29545604, 2018).
alveolar rhabdomyosarcoma (86 papers, 2001 to 2026). A rapidly growing malignant mesenchymal neoplasm. "For example, in alveolar rhabdomyosarcoma (aRMS), the fusion oncogene PAX3::FOXO1 (or PAX7::FOXO1) binds SEs together with other MTFs, including MYOD, MYOG, and MYCN, to sustain proliferation, and their depletion leads to altered proliferation and cell death." (PMID 41444391, 2025). "Alveolar rhabdomyosarcoma (ARMS) is characterized by the presence of the PAX3- or PAX7-FOXO1 fusion." (PMID 32363002, 2020). "The two main subtypes are alveolar rhabdomyosarcoma (ARMS), which is associated with PAX3/7-FOXO1 fusion genes, and embryonal rhabdomyosarcoma (ERMS), which is associated with mutations in common cancer genes such as HRAS, KRAS, NRAS, CTNNB1, PIK3CA and TP531." (PMID 30353028, 2018). "In a majority of alveolar rhabdomyosarcomas (ARMS), PAX3 has been shown to undergo chromosome rearrangement with FOXO1/FKHR." (PMID 31614829, 2019).
Waardenburg syndrome (55 papers, 2011 to 2026). "Hair hypopigmentation and hearing loss occurs in mice or Waardenburg Syndrome patients with hemizygous PAX3/pax3 gene loss or mutation due to missing or defective melanocytes." (PMID 40428399, 2025). "As a case in point, homozygous PAX3 mutations have been reported in type 3 Waardenburg syndrome patients." (PMID 38278860, 2024). "Although type 1 and 3 Waardenburg syndrome patients with Pax3 heterozygous mutation typically exhibit severe-to-profound hearing loss, Sp heterozygous mice display normal hearing as do Pax3-Cre heterozygous mice in this study 18,27." (PMID 38278860, 2024). "Genetic studies suggest that Waardenburg syndrome is caused by mutations of PAX3 and other genes such as MITF, SOX10, EDN3, EDNRB and SNAI21,9,13,35–37." (PMID 38278860, 2024). "Human PAX3 mutations cause Waardenburg syndrome and abnormalities of skin and retinal melanocytes, manifested as congenital hearing loss (~ 70%) and hypopigmentation of skin, hair and eyes." (PMID 38278860, 2024). "Mutations in PAX3 cause Waardenburg syndrome type 1 and Waardenburg syndrome type 3, At the same time, PAX3 plays an important role in the regulation of normal cell apoptosis, proliferation and differentiation." (PMID 39228912, 2024). "Pax3 is also a critical regulator of neural crest induction at the neural border, and when mutated, subjects are born with Waardenburg syndrome or with Sjögren’s syndrome." (PMID 37759439, 2023). "Human PAX3 mutations cause Waardenburg syndrome and abnormalities of melanocytes, manifested as congenital hearing loss and hypopigmentation of skin, hair and eyes." (PMID 37333245, 2023). "Other conditions such as Aland Island Eye disease caused by a mutation in CACNA1F and Waardenburg Syndrome associated with PAX3 mutations can have similar clinical findings of albinism on ocular exam." (PMID 36672876, 2023). "In humans, genetic modification of PAX3 is associated with the etiology of Waardenburg syndrome and SB, suggesting a pathogenic role of the PAX3 gene in both diseases." (PMID 37885410, 2023). "Waardenburg syndrome is susceptible to being misdiagnosed as autosomal recessive due to PAX3 spontaneous mutation and ignores MITF-related freckle phenotype." (PMID 36504663, 2022). "In the case of CHARGE syndrome (n = 4), only one subject carried a detectable CDH7 variant; likewise, in the case of Waardenburg syndrome (n = 2), only one subject carried a detectable PAX3 variant." (PMID 35853923, 2022). "PAX3 is known as key player in cranial neural crest development and is associated with neural crest-related diseases like Waardenburg syndrome, while PAX9 initiates tooth development." (PMID 33271866, 2020). "Waardenburg syndrome is genetically heterogeneous and results from mutations in Sox10, Pax3, Mitf, Snai2, Ednrb, and Edn3, as well as many cases with unidentified mutations." (PMID 32912160, 2020). "Pax3 is required for the development of multiple NC lineages and is implicated in NC disorders observed in humans, including Waardenburg syndrome, which results in hearing defects and craniofacial anomalies." (PMID 32314458, 2020). "Exemplifying this, spinal progenitors harbouring different levels of PAX activity generates distinct combinations of neuronal subtypes and the loss of one single PAX3 allele leads to Waardenburg syndrome, a developmental defect in NCC." (PMID 33175861, 2020). "Recessive and dominant mutations in PAX3 in humans are known to cause Waardenburg syndrome, an autosomal dominant condition that affects neural crest-derived structures and also includes spina bifida as part of its phenotypic spectrum." (PMID 30665459, 2019). "Concerning PAX3, this gene is expressed in the neural crest and is a candidate for Waardenburg syndrome, a clinical condition entailing sensorineural hearing loss and developmental delay." (PMID 30971880, 2019).